APLN (apelin)
Diseases named in the same sentence as APLN in open-access papers (continued):
Sharing a sentence is not in itself a finding about the gene and the disease.
Obesity (continued). "In conclusion, the absence of apelin expression induces marked metabolic and inflammatory disturbances characteristic of obesity." (PMID 34782679, 2021). "Nevertheless, the effects of apelin on glucose homeostasis in models with diet-induced obesity, at present, do not appear clearly coordinated between peripheral tissues and CNS." (PMID 33679444, 2021). "Taking into account, the obesity‐related levels of ELABELA and apelin for an infusion in lean mice could reproduce even more accurately the activation of the apelinergic system in obesity." (PMID 32681609, 2020). "Moreover, a decrease in circulating apelin level in obese children suggest that apelin homeostasis is impaired in the obese state, which could be a warning sign before the emergence of well-known obesity-related metabolic diseases and requires further long-term studies." (PMID 32998691, 2020). "Strikingly, no study has analysed the impact of the obesity‐related increased levels of apelin on tumour growth." (PMID 32681609, 2020). "In the present study, metabolic and weight reducing effects of chronic once daily administration of (Lys8GluPAL)apelin-13 amide and pGlu(Lys8GluPAL)apelin-13 amide were directly compared to the GLP-1 mimetic, liraglutide using a high-fat fed mouse model diet-induced obesity-diabetes (DIO)." (PMID 30157220, 2018). "In attempting to seek possible explanations of significant heterogeneity, stratifying studies that assessed circulating apelin concentration between CAD patients and controls by continent, endpoint, apelin source, matching status, sample size, obesity and hypertension were conducted, respectively." (PMID 28915675, 2017). "Results of these studies indicate that agreement is still lacking on the relationship between apelin levels and obesity, especially in children." (PMID 24475149, 2014). "The absence of an obvious difference in serum Apelin-13 levels between obese men and lean subjects at the beginning of the experiment compelled the authors to conclude that Apelin-13 expression in the body is not sufficiently related to the degree of obesity." (PMID 38089606, 2023). "In this review, we summarize the literatures on the role of the Apelin–APJ system in diabetes and obesity for a better understanding of the mechanism and function of apelin and its receptor in the pathophysiology of diseases that may contribute to the development of new therapies." (PMID 35355561, 2022). "It is conceivable that patients who develop obesity-related cancers such as breast or colorectal may have increased serum apelin due to obesity, not from the presence of cancer." (PMID 36230579, 2022). "Importantly, high levels of apelin and APJ have been found in several cancer types that may be connected with obesity." (PMID 32039239, 2019). "However, how far gut microbiota population contribute to the actions of eCB and apelin/APJ and eCB in obesity is unknown." (PMID 27703805, 2016). "Moreover, type 1 diabetic patients are not obese, suggesting that obesity is probably not the main determinant of increased apelin levels." (PMID 25914650, 2015). "This indicates that obesity and body fat mass may not be the main factors altering circulating apelin levels, and insulin resistance may be more important than obesity in increasing plasma apelin levels in humans." (PMID 23772224, 2013). "Similarly to our results, in a study of children with obesity, apelin-12 concentrations correlated positively with indices of glucose homeostasis, such as glucose, insulin and HOMA-IR, indicating that apelin overexpression might have a protective role against insulin resistance." (PMID 39519480, 2024). "However, obesity and high tumoral apelin expression were not correlated, suggesting that those two parameters could be independently associated with reduced NAC response." (PMID 33972642, 2021).
Obesity (continued). "This study aimed to explore effects of Fusobacterium nucleatum with or without apelin on periodontal ligament (PDL) cells to better understand pathomechanistic links between periodontitis and obesity." (PMID 36902162, 2023). "On the other hand, apelin-transgenic mice failed to gain body weight under a HFD feeding condition for 20 weeks and showed decreased body adiposity and resistance to diet-induced obesity." (PMID 37424869, 2023). "In this study, we comprehensively investigated the effects of 8-week endurance exercise training program on visfatin, chemerin, apelin, and SEMA3C and its relations to changes in the measures of obesity and glucose homeostasis in 40 obese young adults without metabolic derangements." (PMID 32561824, 2020). "APLN shares a close relationship with TNF α expression in adipose tissue, which has led to its consideration as a potential bridge mediator between inflammation and insulin resistance in obesity, though body-mass is likely not a major determinant of its circulating forms." (PMID 40182840, 2025). "Finally, we did not analyse the entire APLN and APLNR genes with obesity." (PMID 32998691, 2020).
diabetes (121 papers, 2012 to 2026). "Benefits of apelin on insulin action would suggest obvious therapeutic potential for diabetes, but some dispute regarding direct effects of apelin on the endocrine pancreas have caused some confusion in this regard." (PMID 35177945, 2022). "This can be explained by that apelin regulates insulin sensitivity and enhances brown adipogenesis in different tissues associated with diabetes." (PMID 35610700, 2022). "As apelin is an adipocytokine closely associated with diabetes, this study explored the clinical significance of serum apelin levels in patients with type 2 DPN before and after treatment." (PMID 33907154, 2021). "Previous studies showed that the rs3115757 polymorphism is associated with the expression level of APLN and the incidence of diabetes and hypertension." (PMID 32849850, 2020). "The secretion and expression of apelin, which is secreted from the heart, blood vessels, and white adipose tissue, are regulated by insulin; thus, apelin is closely related to metabolic syndrome and other disorders caused by diabetes or insulin resistance." (PMID 30696454, 2019). "It showed that the lowermost tertile of apelin was independently associated with sECAS (OR, 5.121; 95% CI, 1.597–16.426) when adjusted for age, gender, hypertension, diabetes, dyslipidemia, MetS, and NIHSS at admission." (PMID 31803136, 2019). "A recent study has reported a significant correlation between single-nucleotide polymorphisms of the apelin gene and diabetes." (PMID 31829402, 2019). "Plasma apelin concentrations were higher in women than in men but they were associated with a risk of diabetes only in men." (PMID 25914650, 2015). "With regards to the association between apelin and diabetes, in a very small study, Dray at al. also found increased apelin plasma levels in diabetic patients (n = 12) compared to controls (n = 11), in line with our observations in a larger cohort." (PMID 23227256, 2012). "In this context, another aim of the current study was to examine the effect of APLN genetic variants on hypertension in patients with diabetes." (PMID 23316219, 2012). "Potentially, apelin levels could serve as a marker for increasedcardiovascular complication risk, making it a valuable tool in the follow‐up of patientswith diabetes." (PMID 41585414, 2025). "Furthermore, in diabetic retinopathy, apelin-13 has been implicated in promoting retinal neovascularization, further illustrating its dual role in diabetes-related complications." (PMID 39857634, 2024). "Since diabetes-associated male reproductive dysfunction is a metabolic disorder, we asked whether activation of APLN/APJ had any effect on the metabolism of Sertoli cells." (PMID 36443325, 2022). "Therefore, targeting APLN/APJ is a promising strategy to ameliorate diabetes-associated subfertility by improving the BTB integrity." (PMID 36443325, 2022). "has proven that apelin can regulate blood glucose levels, and elevated levels of plasma apelin might be beneficial in reducing the risk of diabetes." (PMID 35663309, 2022). "The apelin/apelin receptor signaling pathway, discovered as a vasculogenic guiding factor in zebra fish, is an important regulator of insulin sensitivity, glucose utilization and diabetes risk, and indirect evidence suggests apelin regulates adipose tissue vasculature and adipocyte size." (PMID 35857195, 2022). "It was reported that apelin regulates insulin sensitivity, stimulates glucose utilization and enhances brown adipogenesis in different tissues associated with diabetes 12, 41, indicating the apelin–APJ system as a novel therapeutic target for pharmacological intervention in treating diabetes." (PMID 30868058, 2019). "Subsequently, we hypothesized that the serum level of Apelin-13 may be associated with the occurrence of osteoporosis in patients with Type-2 diabetes mellitus." (PMID 29643899, 2018).
diabetes (continued). "Interestingly, APLN is a known adipokine implicated in coagulation, insulin resistance and diabetes and its higher expression in layers is consistent with the pattern of another pro-inflammatory adipokine in mammal, RBP4." (PMID 29695257, 2018). "In conclusion, the present study has shown that once daily administration of (Lys8gluPAL)apelin-13 amide or pGlu(Lys8gluPAL)apelin-13 amide ameliorated diabetes, evoked weight loss and decreased circulating lipids in high-fat fed mice, with effects similar to or better than liraglutide." (PMID 30157220, 2018). "In diabetic patients apelin-12 concertation was increased, extending susceptibility to diabetes, thus, examining plasma apelin level could be used as a method to predict the development of type 2 diabetes." (PMID 29875677, 2018). "Our data suggest that modification of Sirt3 with apelin could be used as a novel therapy strategy for the treatment of diabetes-associated heart failure." (PMID 29167823, 2015). "Additionally, in patients with type 2 diabetes mellitus, regular exercise training elevates circulating apelin levels, and higher levels of physical activity caused larger increases in apelin levels than lower levels of activity." (PMID 24691252, 2014). "Besides, it seems that the apelin/eNOS axis has been implicated in processes such as glucose uptake and vascular functions, and not surprising that this axis dysfunction is associated with diabetes." (PMID 32908933, 2020). "Binary logistic regression analysis identified apelin-36 and diabetes mellitus as significant predictors at the 5% level, with p-values of 0.045 and 0.036, respectively." (PMID 41598248, 2026). "Aftercontrolling for weekly physical activity apelin levels were significantly differentfor patients with prolonged diabetes as compared to recent onset and controls(p = 0.04 and p = 0.035, respectively)." (PMID 41585414, 2025). "Apelin is also suggested to increase musclemass and reverse age‐related sarcopenia.Sarcopenia is a potential complication in patients with diabetes, and there is someevidence pointing to its occurrence as early as adolescence in T1D." (PMID 41585414, 2025). "Apelin levels were lower in patients with longer diabetes durationcompared with patients with recent onset diabetes and controls (117.9 ± 94.3,228.3 ± 181.6, 224.4 ± 138.4 pg/ml,respectively p = 0.029)." (PMID 41585414, 2025). "While some discrepancies were found, studies describing the relationship between apelin and albuminuria in patients with diabetes showed a positive correlation between the two parameters." (PMID 41515992, 2025). "Based on other findings, apelin alleviates diabetes-induced albuminuria in type 1 diabetes animal models by reducing renal inflammation and hypertrophy." (PMID 38178017, 2024). "Overall, this study highlights a differential role of apelin in diabetes, particularly in its potential involvement in metabolic pathways and glycemic control, with a more pronounced association observed in T2DM." (PMID 39857634, 2024). "An important part appears to be played by apelin in obesity-related disorders, diabetes mellitus, fetal growth disorders, and preeclampsia." (PMID 39457235, 2024). "The present study revealed the nephroprotective and hepatoprotective effects of human WJ-MSCs-CM for the first time in the STZ-induced diabetic rat model through apelin and TGF-β signaling pathways." (PMID 38178017, 2024). "In diabetes-related complications such as diabetic retinopathy and nephropathy, apelin-13 levels are significantly higher in diabetic tissues compared to non-diabetic ones." (PMID 39857634, 2024). "Apelin, whose serum and salivary concentrations are elevated in patients with diabetes and/or periodontitis, is a relatively understudied adipokine in the periodontium." (PMID 39409058, 2024).
diabetes (continued). "Based on empirical evidence, among the adipokines discovered thus far, adiponectin, leptin, resistin, and apelin emerge as the most promising candidates for clinical application, particularly in the realms of myocardial protection and diabetes management." (PMID 39538244, 2024). "Our study confirmed that apelin exhibited antifibrotic and anti-EndMT effects in endothelial cells in diabetic kidneys and hearts and remarkably ameliorated diabetes-induced glomerular damage." (PMID 36785790, 2023). "The apelin/APJ system is involved in the regulation of diabetes and diabetic complications such as diabetic kidney disease." (PMID 36785790, 2023). "Apelin varies according to body mass index, patient age, and the presence of diabetes, or in cases of an inflammatory condition, such as psoriasis." (PMID 37175743, 2023). "Apelin regulates insulin secretion, glucose uptake, lipid oxidation, apoptosis, oxidative stress, and angiogenesis, playing a critical role in diabetes-related complications like cardiovascular diseases, diabetic nephropathy, and endothelial dysfunction." (PMID 37424869, 2023). "As an adipocytokine secreted by and sensed by adipocytes, apelin is necessary for the maintenance of insulin sensitivity and tends to counteract diabetes mellitus." (PMID 36982812, 2023). "The following should be consulted for a more detailed discussion of apelin agonism in disorders of water balance, diabetes mellitus, obesity and metabolic disorders, and apelin analogues and therapeutic agents." (PMID 37956047, 2023). "Serum levels of apelin are lower in COVID-19 patients with concomitant hypertension or in patients with concomitant diabetes mellitus and obesity, making them vulnerable to a more severe disease form." (PMID 37686837, 2023). "Here, we demonstrated that these effects were preserved in hypoxic endothelial cells and ischemic muscle following apelin stimulation despite being exposed to HG levels and diabetes." (PMID 37636297, 2023). "Compared with the control group, diabetic kidneys showed more endothelial cells undergoing EndMT, suggesting that apelin remarkably suppressed diabetes-induced endothelial damage." (PMID 36785790, 2023). "In vivo, apelin ameliorated diabetes-induced renal fibrosis and glomerular damage, and the anti-EndMT effect of apelin was confirmed in endothelial cells of diabetic kidneys." (PMID 36785790, 2023). "Apelin is crucial for controlling insulin secretion and plays a role in the pathogenesis of diabetes complications." (PMID 37706122, 2023). "Those patients who suffered from both diabetes and periodontitis exhibited the highest serum levels of apelin as compared to healthy individuals." (PMID 36902162, 2023). "Collectively, these data suggest that the repressive effect of diabetes on the apelinergic system expression can be overcome by apelin administration, resulting in a proper recovery from tissue ischemia." (PMID 37636297, 2023). "Apelin synthesis in adipocytes is stimulated by insulin and its plasma levels are demonstrated to increase in relation to diabetes mellitus, IR, and hyperinsulinemia." (PMID 35913970, 2022). "A substantial number of clinical studies have been reported apelin levels in body fluids, in both healthy controls and patients with different pathologies (cardiac disease and diabetes, etc.)." (PMID 35610700, 2022). "Recently, there are increasing evidences showing that APLN/APJ plays a role in regulating male fertility and diabetes-associated infertility." (PMID 36443325, 2022). "The reduction of apelin in subjects with diabetes mellitus can worsen blood glucose regulation in these patients when they are infected with COVID-19." (PMID 36352477, 2022). "Here they show that diabetes disrupts the APLN signaling axis in the testes and that spermatogenesis can be restored through treatment with an APLN antagonist." (PMID 36443325, 2022).